WFS1 (wolframin ER transmembrane glycoprotein)
Diseases named in the same sentence as WFS1 in open-access papers (continued):
Sharing a sentence is not in itself a finding about the gene and the disease.
Alzheimer disease (6 papers, 2018 to 2024). A progressive, neurodegenerative disease characterized by loss of function and death of nerve cells in several areas of the brain leading to loss of cognitive function such as memory and language. "Particularly, deficiency of WFS1 increases neurodegeneration in both Drosophila overexpressing human tau and in an Alzheimer’s disease-like mouse model, respectively." (PMID 33693650, 2021). "wfs1-deficient flies were vulnerable to various age-related stressors such as oxidative stress and excitotoxicity, and to neurodegeneration caused by Alzheimer’s disease-related toxic proteins." (PMID 29357349, 2018). "Induced wolframin endoplasmic reticulum transmembrane glycoprotein (WFS1) deficiency has been found to increase tau toxicity, which may play important roles in the development and progression of Alzheimer’s disease." (PMID 36440278, 2022). "Further research is required to fully elucidate WFS1’s role in the cellular pathway, perhaps facilitating the development of new therapeutic strategies for Alzheimer’s disease and sleep disorders." (PMID 39595565, 2024). "WFS1 is being considered a new therapeutic target for different neurodegenerative diseases, particularly Alzheimer’s disease." (PMID 37650104, 2023). "WFS1’s role in various cellular mechanisms, particularly in calcium homeostasis and the modulation of endoplasmic reticulum (ER) stress, suggests its potential involvement in the pathogenesis of Alzheimer’s disease (AD) and sleep disorders." (PMID 39595565, 2024). "To determine whether wfs1 knockdown exacerbated axon degeneration, we used transgenic Drosophila expressing the Alzheimer’s disease-related human tau protein under the control of the pan-retinal GMR-GAL4 driver." (PMID 29357349, 2018). "More interestingly, WFS1 might participate in the pathogenesis of Alzheimer’s disease (AD)." (PMID 36527091, 2022).
autosomal dominant optic atrophy (6 papers, 2014 to 2022). An autosomal dominant hereditary condition characterized by optic atrophy and progressive visual loss. "The thinning of the RNFL layer was segmental in nature compared with other inherited optic neuropathies, such as OPA1-related and WFS1-related dominant optic atrophy, in which more generalized RNFL thinning has been reported in all segments." (PMID 34466801, 2021).
low-frequency sensorineural hearing loss (6 papers, 2014 to 2024). "Dominant mutations in the WFS1 gene are a common cause of low-frequency sensorineural hearing loss." (PMID 26742931, 2016). "Other WFS1-related disorders such as low-frequency sensorineural hearing impairment (LFSNHI) and Wolfram syndrome-like disease with autosomal dominant transmission have been described." (PMID 36816038, 2023).
Optic neuropathy (6 papers, 2010 to 2024). "Hearing appears to deteriorate more progressively for the WFS1 mutation and these patients also develop optic neuropathy." (PMID 20069065, 2010). "As this genetic disease is recessive, this variant can only confer susceptibility to optic neuropathy but it could act synergistically with the WFS1 variant to increase susceptibility, to optic nerve damage." (PMID 38796496, 2024). "Several of these genes, such as WFS1, SPG7, and NR2F1, are common causes of hereditary optic neuropathies and none of them has been previously associated with alcohol susceptibility, to the best of our knowledge." (PMID 38796496, 2024).
Anxiety (5 papers, 2008 to 2025). Intense feelings of nervousness, tension, or panic often arise in response to interpersonal stresses. "Some variants in the Wolfram Syndrome 1 gene (WFS1) were associated with various neuropsychiatric disorders in humans, such as aggressiveness, impulsivity and anxiety." (PMID 32723293, 2020). "Similarly, heterozygous carriers of WFS1 mutations have an increased incidence of psychiatric disorders including endogenous depression, suicide attempts, short-term memory loss, and anxiety." (PMID 18660851, 2008).
nonsyndromic hearing loss (5 papers, 2014 to 2023). "Our data propose that the WFS1-p.L187F mutation is the pathogenic variant for autosomal dominant nonsyndromic hearing loss." (PMID 34222109, 2021). "Of the 23 probands, six had mutations in DFNA genes [WFS1 (n = 2), COCH, ACTG1, TMC1, and POU4F3] known to cause autosomal dominant nonsyndromic hearing loss." (PMID 25388789, 2014).
Ataxia (4 papers, 2021 to 2025). Ataxia refers to impaired coordination of voluntary muscle movement. "WFS1-associated disorders can present as progressive neurodegenerative conditions such as cerebellar ataxia, brainstem dysfunction, peripheral neuropathy, and epilepsy." (PMID 36967753, 2023). "Genetic testing, which covered over 200 ataxia genes, identified only one common VUS in WFS1, and no clear disease-causing de novo variants." (PMID 38239855, 2023).
Intellectual disability (4 papers, 2020 to 2025). "In the context of this 4p deletion, reduced WFS1 expression could, alongside DRD5 haploinsufficiency, contribute to the patient’s intellectual disability." (PMID 41185014, 2025).
sensorineural hearing loss (4 papers, 2020 to 2026). "Fifteen participants with autosomal dominant WFS1 pathogenic variants presenting with both optic nerve atrophy and sensorineural hearing loss were included." (PMID 42001184, 2026). "We found 3.9% of sporadic nonsyndromic sensorineural hearing loss is caused by de novo WFS1 mutations.Our data provide that the de novo p.E864K mutation is first identified and de novo p.A684V mutation is likely to be a mutational hot spot in WFS1." (PMID 32567228, 2020).
auditory neuropathy (3 papers, 2010 to 2025). A hearing disorder characterized by impaired transmission of signals through the auditory nerve, resulting in mild to severe hearing loss and poor speech perception. "In addition, patients with missense mutations in WFS1, causing DFNA6/14, also have sensorineural hearing loss and no auditory neuropathy." (PMID 20069065, 2010).
Brain atrophy (3 papers, 2018 to 2023). Partial or complete wasting (loss) of brain tissue that was once present. "Most WS patients die prematurely in association with severe neurological disabilities as a result of brain atrophy; however, the mechanisms underlying neurodegeneration caused by WFS1 deficiency remain elusive." (PMID 29357349, 2018). "Previous publications also support the WFS1 involvement in retinal and optic nerve degeneration and brain atrophy, but this paper was direct evidence for the WFS1 involvement in the aggregation of other proteins." (PMID 37759745, 2023).
epilepsy (3 papers, 2018 to 2024). A brain disorder characterized by episodes of abnormally increased neuronal discharge resulting in transient episodes of sensory or motor neurological dysfunction, or psychic dysfunction. "Regarding the etiology of epilepsy, five (11.1%) were genetic, including one with SCN2A mutation, one with KCNA2 mutation, one with MBD5 mutation, one with WFS1 mutation, and one with OCRL mutation." (PMID 38419715, 2024). "In a rat model of epilepsy induced by kainic acid toxicity, Wfs1 mRNA levels are markedly reduced in the hippocampal CA3 region." (PMID 29357349, 2018).
Insulin resistance (3 papers, 2015 to 2024). Increased resistance towards insulin, that is, diminished effectiveness of insulin in reducing blood glucose levels. "Two other upregulated genes Wfs1 and Cck, which involved in the regulation of the system process and nervous system, were associated with T2D and insulin resistance, respectively." (PMID 31579613, 2019). "Similarly the altered metabolic phenotype we observed in the BTBR mice, potentially associated with Wfs1 expression modulation, have been corroborated in the past, with BTBR mice having increased insulin resistance and higher fasting insulin levels." (PMID 26635614, 2015).
neuroblastoma (3 papers, 2018 to 2023). Neuroblastoma (NB) is the most common solid, extracranial childhood tumor. "One caveat is that SERCA protein level is increased in primary islets isolated from Wfs1 conditional knock-out mice, as well as in MIN6 cells and neuroblastoma cell line with WFS1 knocked down." (PMID 37399203, 2023). "They demonstrated a novel interaction between Wfs1 and SERCA2b by co-immunoprecipitation in COS7 cells and with endogenous proteins in human neuroblastoma cells." (PMID 29511163, 2018).
retinitis pigmentosa (3 papers, 2023 to 2024). Retinitis pigmentosa (RP) is an inherited retinal dystrophy leading to progressive loss of the photoreceptors and retinal pigment epithelium and resulting in blindness usually after several decades. "Indeed, Patient 46 presents GJB2-associated HL and RPGR-associated retinitis pigmentosa while Patient 50 is affected by WFS1-related HL and pseudoxanthoma elasticum due to an ABCC6 mutation." (PMID 36979683, 2023). "Recently, pathogenic variants in the WFS1/RP1/NOD2 genes have been shown to cause congenital cataract, retinitis pigmentosa, and Crohn’s disease in a five generation British family." (PMID 38984127, 2024).
schizophrenia (3 papers, 2017 to 2025). A major psychotic disorder characterized by abnormalities in the perception or expression of reality. "Mutations in the WFS1 gene have been associated with the emergence of psychotic and schizophrenia-like symptoms, but these observations are interpreted descriptively rather than as evidence of a direct genetic–psychiatric link." (PMID 41008710, 2025). "Interest in WFS1’s role in schizophrenia stems from observations that mutation carriers show an increased likelihood for psychiatric hospitalization." (PMID 29249829, 2017). "Among these, the four genes most strongly altered in schizophrenia were WFS1 (P = 1.8×10−7), angiotensinogen (AGT, P = 1.3×10−6), LRP4 (P = 2.7×10−6), and TNS2 (P = 9.3×10−4), all of which were increased in schizophrenia." (PMID 29249829, 2017).
Wolfram syndrome type 2 (3 papers, 2017 to 2025). "The causative gene of WFS1-SD is WFS1, contrarily from the less common Wolfram syndrome type 2 (WS2) which is caused by autosomal recessive mutations of the CISD2 (CDGSH iron-sulfur domain-containing protein 2) gene." (PMID 37333802, 2023). "The majority of patients harbour pathogenic WFS1 mutations, but recessive mutations in a second gene, CISD2, have been described in a small number of families with Wolfram syndrome type 2 (WFS2)." (PMID 28335035, 2017). "The majority of patients harbour pathogenic WFS1 mutations, but recessive mutations in a second gene, CISD2 (CDGSH iron-sulfur domain-containing protein 2), have been described in a few patients with Wolfram syndrome type 2 (WFS2, OMIM #604928)." (PMID 28335035, 2017).
amyotrophic lateral sclerosis (2 papers, 2023 to 2024). Amyotrophic lateral sclerosis (ALS) is a neurodegenerative disease characterized by progressive muscular paralysis reflecting degeneration of motor neurons in the primary motor cortex, corticospinal tracts, brainstem and spinal cord. "Riluzole, one of the few drugs approved for the treatment of amyotrophic lateral sclerosis (ALS), regulated aberrant glutamate transporter expression in Wfs1-deficient cerebral organoids, thereby restoring synapse formation and functionality." (PMID 37107585, 2023).
breast carcinoma (2 papers, 2019 to 2023). "For example, genes such as VCP, which has a role in breast cancer, and WFS1, which has a role in COVID-19, are known to show a role in FTD as well." (PMID 37834358, 2023).
cardiomyopathy (2 papers, 2023). A disease of the heart muscle or myocardium proper. "Patients with WFS1 may have muscular dystrophies and cardiomyopathy, and, therefore, the muscular phenotype requires more attention." (PMID 37759745, 2023). "However, the relationships between WFS1, mitochondrial function, and cardiomyopathy need to be further studied." (PMID 36967753, 2023).
cognitive decline (2 papers, 2021 to 2025). "Genetic analysis showed that homozygosity for pathogenic WFS1 variants was overrepresented across all symptom categories (≥62%), reaching the highest levels in cognitive decline (81%), anosmia (78%), and adiadochokinesia (82%)." (PMID 41464213, 2025).
Cognitive impairment (2 papers, 2023 to 2025). Abnormal cognition is characterized by deficits in thinking, reasoning, or remembering. "Additionally, a mutation in the WFS1 gene (c.1756G>A p.A586T) is responsible for early clinical features of cognitive impairment and recurrent ischemic stroke." (PMID 37510352, 2023).
colon cancer (2 papers, 2022 to 2024). "Finally, we determined that knockdown of the expression of WFS1 inhibits the proliferation of colon cancer cells." (PMID 36445321, 2022).
dementia (2 papers, 2021 to 2023). Loss of intellectual abilities interfering with an individual's social and occupational functions. "Therefore, we can conclude that WFS1 deficiency is directly related to the neurodegeneration, and we have also shown the potential of the WFS1 gene as a therapeutic opportunity for the neurodegeneration and dementia." (PMID 37759745, 2023). "WFS1 gene transfer has been shown to be efficient against tau aggregation and can, therefore, stop the progression of dementia." (PMID 37759745, 2023).
Infertility (2 papers, 2019 to 2023). "BAX, LMNA, and WFS1 were associated with an infertility-related condition in DisGeNET database." (PMID 31694346, 2019).
neuropathy (2 papers, 2023 to 2024). A disorder affecting the nervous system that manifests with pain, tingling, numbness, and/or muscle weakness. "Current studies on WS neuropathy mainly focus on investigating the role of WFS1 in dysfunction and degeneration of neurons in Drosophila, fly, and mouse model." (PMID 36750736, 2023).
Parkinson disease (2 papers, 2016 to 2021). A progressive degenerative disorder of the central nervous system characterized by loss of dopamine producing neurons in the substantia nigra and the presence of Lewy bodies in the substantia nigra and locus coeruleus. "There is also some limited evidence in the literature that WFS1 is associated with Parkinson pathways." (PMID 27434582, 2016). "We also demonstrate that the mechanism linking WFS1 deficiency-related ER stress with impaired mitochondrial dynamics involves two Parkinson’s disease-related proteins, PINK1 and Parkin." (PMID 27434582, 2016). "Furthermore, WFS1 polymorphisms and mutations have been associated with Parkinson’s disease as well as with a variety of psychiatric illnesses." (PMID 33693650, 2021).
prediabetes (2 papers, 2012 to 2023). "In the current study, heterozygous TC of the WFS1-rs1801214 variant located in the coding sequence showed a statistically significant association with prediabetes (0.60; 95% CI 0.44–0.80; p < 0.01)." (PMID 36980809, 2023). "Furthermore, heterozygous GA of rs4812829 (HNF4A), rs5945326 (DUSP9), and rs11634397 (ZFAND6), along with heterozygous TC of rs1801214 (WFS1), were associated with a decreased risk for prediabetes." (PMID 36980809, 2023). "In summary, we found significant associations between prediabetes risk and five variants closely related to the FTO, HNF4A, WFS1, DUSP9, and ZFAND6 genes (rs4812829, rs1801214, rs5945326, rs11642841, and rs11634397) among Saudi Arabian adults." (PMID 36980809, 2023).
tauopathy (2 papers, 2018 to 2022). Neurodegenerative disorders involving deposition of abnormal tau protein isoforms (tau proteins) in neurons and glial cells in the brain. "This outcome is consistent with recent work showing that Wfs1 expression protects EC2 neurons from tauopathy and degeneration." (PMID 36468693, 2022). "In support of this hypothesis, wfs1 expression was induced by aging and stressors, and neuronal knockdown of wfs1 rendered neurons vulnerable to oxidative stress-, altered neuronal excitability- or Alzheimer’s associated tauopathy-induced behavioral deficits and neurodegeneration." (PMID 29357349, 2018). "Although wfs1 knockdown alone did not promote ER stress, it increased the susceptibility to oxidative stress-, excitotoxicity- or tauopathy-induced behavioral deficits, and neurodegeneration." (PMID 29357349, 2018).
age-related hearing loss (1 paper, 2022). "Some studies have shown that WFS1 mutations also play an important role in age-related hearing loss (ARHL)." (PMID 36564540, 2022). "Generally, the majority of NSHL patients with mutations in WFS1 experienced hearing loss change from low frequency to full frequency, with no or slow progression except for presbycusis." (PMID 36564540, 2022).
Atrophy (1 paper, 2021). Any weakening or degeneration, especially through lack of use. "Here, in vivo MRI revealed that optic nerve volume was also decreased in saline-treated Wfs1 KO animals at the age of 17 months (p < 0.001) and the 16-month treatment with liraglutide protected the optic nerve from atrophy." (PMID 34831417, 2021). "Additionally, we have previously revealed increased retinal ganglion cell death, decreased visual acuity and clear degenerative processes in Wfs1 KO rats’ optic nerves and resultant atrophy." (PMID 34831417, 2021).
autoimmune disease (1 paper, 2024). A disorder resulting from loss of function or tissue destruction of an organ or multiple organs, arising from humoral or cellular immune responses of the individual to their own tissue constituents. "In addition to the IKBKE gene, the WFS1 gene has been identified as a gene associated with “autoimmune diseases,” as defined by The Human Gene Mutation Database." (PMID 39524436, 2024).
hearing disorder (1 paper, 2021). A disorder characterized by the partial or complete loss of the ability to detect sounds due to damage to the ear structures or inability of the brain to properly interpret or process the auditory signals it receives from the anatomic structures of the ear. "WFS1 is a reticulum endoplasmic cation channel playing a role in Ca2+ homeostasis, and is responsible for the hearing disorder Wolfram Syndrome Type l." (PMID 34137817, 2021).